DUOX1 (dual oxidase 1)
Diseases named in the same sentence as DUOX1 in open-access papers (continued):
Sharing a sentence is not in itself a finding about the gene and the disease.
tumor (continued). "This may indicate that DUOX1 silencing is directly proportional to tumor severity." (PMID 41556052, 2026). "Moreover, the histopathological and immunohistochemical characterization of the tumor samples shows that they are very heterogeneous in relation to the expression of hormone receptors and proliferation, but nevertheless, DUOX1 mRNA was lower in almost all of them, when compared to their controls." (PMID 29849884, 2018). "Among the distinctively upregulated genes in low EGF treatment, we found genes related to anti-tumor immunity, sperm flagellar assembly, and mitogenesis (SLC6A6, DNAH17, DUOX1)." (PMID 39694501, 2025). "NOX2, NOX4, and NOX5 mRNA levels increased with tumor progression stages, while NOX1 and DUOX1 expression decreased in more advanced stages." (PMID 38542437, 2024). "We performed meta-analysis on 8 microarray studies and identified six significantly up- (PLAU, FN1, CDCA5) and down-regulated (CRNN, CLEC3B and DUOX1) genes which were subsequently quantified by RT-qPCR in 100 HNSCC patient margin and core tumour samples." (PMID 31443700, 2019). "In this study, we further investigate the impact of DUOX1, GLS2 and FBP1 genes expression on liver patients’prognosis after tumor resection." (PMID 27079415, 2016). "Furthermore, heatmap analysis revealed that TREX1 and RRM2 expression levels were significantly higher in tumor tissues compared to normal tissues, whereas GPX2, DUOX1, and DUOX2 were expressed at lower levels in tumor tissues." (PMID 41346575, 2025). "DUOX1 expression was found to be lower in liver cancer tissues and liver cancercell lines in comparison to non-tumor tissues and immortalized non-tumor celllines." (PMID 32453337, 2020). "As DUOX1 is expressed in mammary nontumor cells, we decided to compare DUOX1 expression between nontumor and tumor breast cell lines and human breast tissues." (PMID 29849884, 2018). "Although, DUOX1, GLS2 and FBP1 acts as liver tumor suppressor and mechanisms about tumor inhibiting of the three genes have been studied, the specific associations between prognosis of liver patients and expression of these three genes still remains unknown." (PMID 27079415, 2016). "According to the results of Fisher’s exact test and computational model (MLP and discriminant analysis), ultimately, Cox multivariate regression analysis was performed included the factors such as DUOX1, GLS2, FBP1, age, intrahepatic metastasis, tumor stage, histological grade and HBsAg." (PMID 27079415, 2016). "Importantly, when comparing tumor breast tissue samples with nontumor samples from the same patient, we observed that tumor samples expressed significantly less DUOX1 mRNA levels." (PMID 29849884, 2018).
infection (27 papers, 2011 to 2024). The state of being infected such as from the introduction of a foreign agent such as serum, vaccine, antigenic substance or organism. "While Mabs S did not significantly modulate the expression of NOX1 and DUOX1 oxidases, we measured a significant increase in DUOX1 expression upon Mabs R infection, suggesting enhanced ROS production by this variant." (PMID 37619220, 2023). "Another limitation is the lack of confirmation of the B cell immunostaining by flow cytometry that shows higher expression in Mtb-infected WT mice at 30 days post-infection compared to Duox1-deficient mice." (PMID 36936954, 2023). "In contrast, B cell staining in the spleen at 30 days post-infection is comparable between Mtb-infected Duox1 KO and WT animals." (PMID 36936954, 2023). "Gating overlay of lymphoid cell subsets in t-sne dimension 1 and 2 indicated lower density of CD4 and CD45 clusters in the spleen at 30 days post-infection, while the density of clusters remained identical for WT and Duox1 KO at 1 day post-infection." (PMID 36936954, 2023). "Our data indicate that both Duox1 KO and WT mice have significantly higher inflammation in the lung tissue and airways at 4 weeks post-infection upon Mtb infection compared to mice at day 1 post-Mtb infection." (PMID 36936954, 2023). "None of the cytokines/chemokines was significantly different between WT and Duox1 KO at 1 day post-infection." (PMID 36936954, 2023). "Duox2 is mainly involved in responses to infection and inflammation, whereas Duox1 plays an important role in defense and mucus production." (PMID 23691121, 2013). "Of key significance is the demonstration that ROS produced by Ce-Duox1/BLI-3 is the source of oxidative stress triggering SKN-1 activity during infection." (PMID 22216003, 2011). "We previously demonstrated that ROS are generated during infection in the model host Caenorhabditis elegans by the dual oxidase Ce-Duox1/BLI-3." (PMID 22216003, 2011). "Evidence is also presented that the ROS produced by Ce-Duox1/BLI-3 is the source of SKN-1 activation via p38 MAPK signaling during infection." (PMID 22216003, 2011). "The goal of this work was to determine if infection, by triggering ROS release by Ce-Duox1/BLI-3, induces an oxidative stress response in the host as part of the overall response to the pathogen." (PMID 22216003, 2011). "Duox1 deficiency did not affect the frequencies of lymphoid or myeloid cells at 30 and 90 days post-infection either." (PMID 36936954, 2023). "In the aggregate, these studies suggest that variants in the CLEC7A/PLCG2/DUOX1/DUOXA1 pathway are not risk factors for primary infection but rather for control of infection (CLEC7A) and dissemination (PLCG2/DUOX1/DUOXA1)." (PMID 37233265, 2023). "However, the density of CD4+ cells inside the T cell cluster is lower in Duox1 KO at 30 day post infection compared to WT." (PMID 36936954, 2023). "However, at 30 days post-infection, the number of B cells is significantly higher in WT mice than in Duox1 KO mice (p≤ 0.05)." (PMID 36936954, 2023). "To further investigate a possible role for Duox1 in the immune responses against Mtb, we harvested the lungs of Mtb-infected WT and Duox1 KO mice at 1 and 30 day(s) post-infection, and proceeded with immunofluorescence staining using a B cell-specific antibody (anti-mouse CD45R)." (PMID 36936954, 2023). "Taken together, these data suggest variants in the CLEC7A/PLCG2/DUOX1/DUOXA1 pathway are not risk factors for primary infection but rather for control of infection (CLEC7A) and dissemination (PLCG2/DUOX1/DUOXA1)." (PMID 36166305, 2022). "Mtb-infected lungs at 1 day post-infection exhibit undetectable MPO while high levels of MPO are evident inside inflammatory cell aggregates at 30 days post-infection in both WT and Duox1 KO mice." (PMID 36936954, 2023).
infection (continued). "In contrast, the expression of ROS-related genes (HPX2, HPX7, HPX8A, HPX8B, HPX8C, MnSOD1 and TPX2) was inhibited in the Ae. aegypti midgut 1 day after infection with Plasmodium gallinaceum, whereas DBLOX, DUOX1, TPX3 and TPX2 levels were induced." (PMID 30986216, 2019). "Herein, an important connection between ROS generation by Ce-Duox1/BLI-3 and upregulation of a protective transcriptional response by SKN-1 is established in the context of infection." (PMID 22216003, 2011). "To assess a possible Duox1-dependent change in MPO levels following Mtb infection, we collected BAL fluids, sera and lung homogenates from Mtb-infected Duox1 KO and WT mice at 1 and 30 day(s) post-infection." (PMID 36936954, 2023). "Mtb titers in the lung, spleen and liver were not different 30 days after infection between WT and Duox1 KO mice." (PMID 36936954, 2023). "However, at 30 days post-infection, TNF-α, IL-6, KC, CCL3, CCL2, CCL20, CXCL11, CCL11), CCL27, CXCL5, CXCL12 and CCL5 were all significantly higher in the BAL fluid of Duox1 KO compared to WT mice." (PMID 36936954, 2023). "Our results show that, compared to WT mice, CFUs in Mtb-infected Duox1 KO mice were not significantly different in the lung, spleen or liver at days 1, 30 or 90 post-infection, respectively." (PMID 36936954, 2023). "Quantification of green fluorescence indicative of Mtb burden did not yield significant differences between WT and Duox1 KO mice neither at 1 nor 30 day(s) post-infection." (PMID 36936954, 2023). "Our results show that B cell numbers in the lung tissues (not BAL) at 1 day post-infection are the same between WT and Duox1 KO mice." (PMID 36936954, 2023). "It is noteworthy that within our cohort, 26 patients with additional infections carried damaging variants in CLEC7A, PLCG2, or DUOX1/DUOXA1, compared with 6 of 27 patients without additional serious infections (n = 26 of 40 vs. 6 of 27; P = 0.001)." (PMID 36166305, 2022). "Expression of NOX1-5 and Duox1-2 was examined in the gastric cell line; however, expression was not affected by the infection." (PMID 23646188, 2013). "The precise role(s) of ROS generated by Ce-Duox1/BLI-3 in protecting the worm from infection is not yet completely understood, though this study implicates an important signaling function." (PMID 22216003, 2011).
bacterial infections (5 papers, 2019 to 2023). "OSCN- kills bacteria and viruses in vitro, but the role of this Duox1-based system in bacterial infections in vivo remains largely unknown." (PMID 36936954, 2023).
infectious disease (2 papers, 2022 to 2023). A disorder directly resulting from the presence and activity of a microbial, viral, or parasitic agent in humans. "Two members of the NADPH oxidase (NOX) family, including the DUOX1 and DUOX2 proteins, are potential therapeutic targets against infectious diseases caused by the influenza A virus." (PMID 36093436, 2022). "To extend these findings to other infectious diseases models, we assessed whether Duox1 prevents or limits Mtb infection, reduces or limits bacterial growth and dissemination, or eliminates or reduces lung pathology in vivo." (PMID 36936954, 2023).
inflammation (1 paper, 2013). Aberrant reaction of the microcirculation characterized by movement of fluid and leukocytes from the blood into extravascular tissues. "Except the role of Duox1 in mucus regulation, we additionally found DPI significantly reduced neutrophils of BALF and lung tissues in mice, which suggested Duox1 may play an important role in PA-LPS-induced airway inflammation." (PMID 23691121, 2013).
DUOX1 also shares sentences with these, for which no sentence is quoted: Immunodeficiency (4 papers); pancreatic cancer (4); dyshormonogenesis (2); gastrointestinal infections (2); Parkinson disease (2); Alzheimer disease (1); cardiovascular disease (1); celiac disease (1); chronic granulomatous disease (1); chronic pancreatitis (1); clear cell renal cell carcinomas (1); colorectal cancer (1); Crohn disease (1); diabetes (1); diabetic kidney disease (1); dwarfism (1); E. coli infection (1); endocervical adenocarcinoma (1); gastric tumors (1); Granuloma (1); Hyperglycemia (1); Hyperoxaluria (1); hypoxia (1); inflammatory bowel disease (1); Lung Injury (1); myocardial ischemia (1); Nasal polyposis (1); Obesity (1); osteopetrosis (1); parasite (1).
A further 15 diseases each share a sentence with DUOX1 in 1 paper.